TFAP2E (transcription factor AP-2 epsilon)
Description:
Sequence-specific DNA-binding protein that interacts with inducible viral and cellular enhancer elements to regulate transcription of selected genes. AP-2 factors bind to the consensus sequence 5'-GCCNNNGGC-3' and activate genes involved in a large spectrum of important biological functions including proper eye, face, body wall, limb and neural tube development. They also suppress a number of genes including MCAM/MUC18, C/EBP alpha and MYC. AP-2-epsilon may play a role in the development of the CNS and in cartilage differentiation (By similarity).
Synonyms: AP2E; AP-2epsilon
Tractability: PROTAC: ubiquitination databases record sites on it.
Gene: Protein-coding gene on chromosome 1 (35,573,314 to 35,595,328, forward strand). Ensembl gene ENSG00000116819.
Subcellular location: Nucleus
Pathways (Reactome):
Gene expression (Transcription): Activation of the TFAP2 (AP-2) family of transcription factors; Negative regulation of activity of TFAP2 (AP-2) family transcription factors
Gene Ontology:
Molecular function: sequence-specific double-stranded DNA binding; DNA-binding transcription activator activity, RNA polymerase II-specific; DNA-binding transcription factor activity, RNA polymerase II-specific; RNA polymerase II transcription regulatory region sequence-specific DNA binding; DNA binding; DNA-binding transcription factor activity; identical protein binding; RNA polymerase II cis-regulatory region sequence-specific DNA binding
Biological process: positive regulation of transcription by RNA polymerase II; regulation of cell population proliferation; regulation of DNA-templated transcription
Cellular component: chromatin; nucleus
Genetic constraint (gnomAD): Loss-of-function variants: 30 observed, 28.69 expected, observed/expected ratio (o/e) 1.05, 90% interval 0.78 to 1.42. The synonymous counts are far from expectation, so gnomAD's model fits this gene poorly and the ratio says little. Missense variants: 567 observed, 501.08 expected, observed/expected ratio (o/e) 1.13, 90% interval 1.05 to 1.21. Synonymous variants: 318 observed, 234.91 expected, observed/expected ratio (o/e) 1.35, 90% interval 1.23 to 1.49.
Homologues: Orthologues: chimpanzee TFAP2E (99% identical), macaque TFAP2E (98% identical), pig TFAP2E (94% identical), rat Tfap2e (94% identical), mouse Tfap2e (93% identical), dog TFAP2E (83% identical), rabbit TFAP2E (80% identical), tropical clawed frog tfap2e (74% identical), guinea pig TFAP2E (68% identical), zebrafish tfap2e (67% identical), Drosophila melanogaster TfAP-2 (47% identical), Caenorhabditis elegans aptf-1 (30% identical), and 3 more. Paralogues in human: TFAP2B (65% identical), TFAP2A (61% identical), TFAP2C (55% identical), TFAP2D (49% identical).
Diseases named in the same sentence as TFAP2E in open-access papers:
TFAP2E is named in the same sentence as 31 diseases in open-access papers, as found by Europe PMC text mining. Sharing a sentence is not in itself a finding about the gene and the disease. The quoted sentences say what the papers report.
colorectal cancer (6 papers, 2014 to 2024). A primary or metastatic malignant neoplasm that affects the colon or rectum. "Several studies have revealed that hypermethylation of the TFAP2E gene is correlated with early tumor stages, low invasion, reduced lymph node metastasis, and favorable prognosis in colorectal cancer." (PMID 37291585, 2023). "For instance, hypermethylation of the transcription factor AP-2 epsilon (TFAP2E) affects the therapeutic efficacy of 5-FU based chemotherapy in colorectal cancer and GC." (PMID 29383097, 2017). "Epigenetic alteration of the TFAP2E gene has also been commonly reported in selected human cancers, including prostate cancer and colorectal carcinoma." (PMID 24781529, 2014). "In addition, several investigations on TFAP2E have shown a tumor suppressive influence, and decreased expression levels indicate promoted oncogenesis, stemness and chemoresistance in several types of cancers, including colorectal cancer, gastric cancer, neuroblastoma and skin neoplasia." (PMID 37291585, 2023). "These enhanced effects were concomitant to TFAP2E upregulation and DKK4 downregulation, as shown with 5-FU resistance in colorectal cancer." (PMID 29383097, 2017). "TFAP2E, on the other hand, perturbs the Wnt/β-catenin signaling by transcriptionally inhibiting the expression of dickkopf Wnt signaling pathway inhibitor 4 (DKK4), an antagonist of Wnt signaling that occupies the Wnt coreceptor, in colorectal cancer." (PMID 37291585, 2023). "But a recent large-scale multicenter cohort study indicated that TFAP2E methylation and expression may not play a major role in predicting response to 5-FU-based chemotherapy in patients with colorectal cancer." (PMID 37859819, 2023).
gastric cancer (5 papers, 2017 to 2024). A primary or metastatic malignant neoplasm involving the stomach. "Besides, in gastric cancer, the methylation status of TFAP2E is also reported to be involved in the 5-FU response, and epigenetic drugs that target DNA methylation are able to rescue TFAP2E-mediated 5-FU sensitivity in gastric cancer." (PMID 37291585, 2023). "The nanoparticles could release drugs in response to the overexpression of matrix metalloproteinases (MMP2/9) and collagenase IV in tumors and restore the expression of TFAP2E through DNA demethylation to resensitize gastric cancer cells to chemotherapy drugs." (PMID 36599655, 2023). "Hypermethylation of the transcription factor AP-2 epsilon (TFAP2E) gene affects 5-fluorouridine (5-FU) resistance in gastric cancer (GC) patients." (PMID 29383097, 2017).
melanoma (4 papers, 2010 to 2024). A malignant, usually aggressive tumor composed of atypical, neoplastic melanocytes. "Further, we demonstrated the regulation of TFAP2E by HIF in this present study in malignant melanoma and a previous study in cartilage, which also links AP2ε expression to stem-cell-like features." (PMID 38773108, 2024). "Downregulation of the transcription factor gene Tfap2e has previously been shown to mediate melanoma invasion and clustering." (PMID 39284707, 2024). "In zebrafish melanoma Tfap2a and Tfap2e also appear to act redundantly to promote proliferation and, interestingly, to suppress cell adhesion and cell migration." (PMID 35580127, 2022). "We detected higher levels of TFAP2E message in three independent isolates of primary melanocytes, consistent with microarray data indicating expression of TFAP2E in melanocytes and melanoma cell lines." (PMID 20862309, 2010). "Interestingly, in zebrafish melanoma, low tfap2e expression correlates with increased metastases." (PMID 35580127, 2022).
colon cancer (2 papers, 2008 to 2018). "Our data identified TFAP2C and TFAP2E as potentially important new targets of transcriptional silencing in colon cancer." (PMID 18446232, 2008). "In a panel of 20 colon cancer cases, all these genes except IRX5, TFAP2E and TFAP2C showed significantly higher methylation in cancer by t-test analysis (P<0.001 for NKX2-5, DPYS SPOCK2, GALR2 and SLC16A12; P = 0.008 for FOXN4)." (PMID 18446232, 2008).
esophageal squamous cell carcinoma (2 papers, 2023 to 2024). Esophageal squamous cell carcinoma (ESCC) is a type of esophageal carcinoma (EC) that can affect any part of the esophagus, but is usually located in the upper or middle third. "Finally, AP-2ε was identified as a definite risk marker for esophageal squamous cell cancer based on the significant differences in TFAP2E methylation levels between the groups with high and intermediate risk of cancer." (PMID 39273087, 2024). "The comparison of aberrant mutations (C→A) as well as the methylation changes of TFAP2E in esophageal squamous cell carcinoma (ESCC) and the nearby healthy esophageal mucosal cells of Taiwanese ESCC patients may possibly be indicative of esophageal cancer risks." (PMID 36845258, 2023).
neuroblastoma (2 papers, 2018 to 2023). Neuroblastoma (NB) is the most common solid, extracranial childhood tumor. "In neuroblastoma, adriamycin (ADR)-mediated induction of the CDK inhibitor P21 is upregulated in the absence of TFAP2E, indicating the implication of TFAP2E and P21 signaling pathway." (PMID 37291585, 2023).
rectal cancer (2 papers, 2015 to 2019). A primary or metastatic malignant neoplasm that affects the rectum. "They found that patients with either primary rectal cancer or metastatic colorectal cancer with TFAP2E gene hypermethylation showed subsequent reduction in TFAP2E protein expression and poor response to treatment as assessed both histologically and by radiological criteria." (PMID 26203306, 2015). "Ebert and colleagues demonstrated the association of hypermethylation of the Transcription Factor Activating Protein 2 Epsilon (TFAP2E) gene with non-response to neoadjuvant chemoradiation in rectal cancer patients." (PMID 31390840, 2019).
adrenocortical carcinoma (1 paper, 2025). "Further species-level verification and prognostic importance nominated three promising pairs: Paraburkholderia fungorum–TFAP2E in adrenocortical carcinoma (ACC), Actinomyces oris–TFAP2E in diffuse large B-cell lymphoma (DLBC), and Cutibacterium granulosum–TFAP2B in stomach adenocarcinoma (STAD)." (PMID 41373739, 2025).
bladder cancer (1 paper, 2023). "In our study, TFAP2E showed the opposite trend in the tumor growth and lymph node metastasis of bladder cancer." (PMID 37859819, 2023). "We used SMART database to analyze the methylation of different TFAP2 family in patients with BLCA, and found that the methylation of TFAP2A, TFAP2B, TFAP2D and TFAP2E in bladder cancer tissues was significantly higher than that in adjacent tissues, while TFAP2C showed the opposite trend." (PMID 37859819, 2023). "However, less study on TFAP2D and TFAP2E was carried out in bladder cancer, and its specific role and mechanism need further research." (PMID 37859819, 2023). "But in general, TFAP2E and TFAP2D has a better prognosis in bladder cancer." (PMID 37859819, 2023).
congenital hydrocephalus (1 paper, 2025). Hydrocephalus that is present at birth. "Although, the hydrocephalus only displayed in a subset of KOCRISPR zfl, indicating incomplete phenotypical penetrance, it nonetheless reinforces the involvement of tfap2e in congenital hydrocephalus." (PMID 39715634, 2025). "Remarkably, we also observed this most-penetrant human phenotype in both, tfap2e+/- and tfap2e-/- KOCRISPR zfl, underpinning the role of tfap2e in congenital hydrocephalus." (PMID 39715634, 2025).
Hydrocephalus (1 paper, 2025). Hydrocephalus is an active distension of the ventricular system of the brain resulting from inadequate passage of CSF from its point of production within the cerebral ventricles to its point of absorption into the systemic circulation. "Remarkably, hydrocephalus was present in four of seven individuals with variants in TFAP2E and was recapitulated in our zfl KD and KOCRISPR models." (PMID 39715634, 2025). "Given the strong genetic evidence by a novel de novo variant in TFAP2E and the phenocopy in our zebrafish model with hydrocephalus and brain phenotype, we see solid evidence that TFAP2E is implicated in the phenotype of D-II:1." (PMID 39715634, 2025). "MO KD and CRISPR/Cas9 knockout of tfap2e in zebrafish revealed hydrocephalus and a significant reduction of brain volume, consistent with a microencephaly phenotype." (PMID 39715634, 2025). "Thus, we postulate that hydrocephalus represents a specific effect following Tfap2e KD." (PMID 39715634, 2025). "However, unlike Tfap2e KD zfl, KOCRISPR larvae did not exhibit a severe phenotype in brightfield imaging and only a subset of tfap2e+/- or tfap2e-/- zfl presented with variable hydrocephalus." (PMID 39715634, 2025).
leukemia (1 paper, 2011). A malignant (clonal) hematologic disorder, involving hematopoietic stem cells and characterized by the presence of primitive or atypical myeloid or lymphoid cells in the bone marrow and the blood. "DPYS, NPM2, OSCP1, PDLIM4 and TFAP2E genes were found hypermethylated, and CDKN2B (p15INK4B) homozygously deleted in the K562 leukemia cell line." (PMID 21760961, 2011).
lung carcinoma (1 paper, 2023). "The TFAP2E gene seem to be the least studied of the family and no original reports concerning this gene expression level in lung cancer patients were found; nonetheless, through our analysis overexpression was found in LUAD, but not in LUSC patients in the TIMER, but not the GEPIA database." (PMID 36831334, 2023).
lymph node metastasis (1 paper, 2023). "However, analysis showed that lymph node metastasis may be significantly associated with high expression of TFAP2A, TFAP2C, and TFAP2E." (PMID 37859819, 2023).
lymphoma (1 paper, 2025). A malignant (clonal) proliferation of B- lymphocytes or T- lymphocytes which involves the lymph nodes, bone marrow and/or extranodal sites. "The increased number of females observed in a group with higher Actinomyces oris abundance and TFAP2E expression may reflect gender-specific immune-microbiome interactions, consistent with emerging evidence of gender-dependent effects of the microbiota on lymphoma progression." (PMID 41373739, 2025).
metabolic syndrome (1 paper, 2020). A cluster of metabolic risk factors for CARDIOVASCULAR DISEASES and TYPE 2 DIABETES MELLITUS. "Among the two CpGs, one was located within an intergenic region (locus 7q31.3) nearby the WNT16-FAM3C-CPED1 locus, previously associated with metabolic syndrome, whereas the other was located within the TFAP2E gene locus." (PMID 33003475, 2020).
myomatous neoplasm (1 paper, 2020). A benign or malignant mesenchymal neoplasm arising from smooth, skeletal, or cardiac muscle. "RIPK3, TFAP2E and TMEM214 were good candidates for the non-neural crest tumors since they are mutated in sarcomas (TCGA SARC), myomatous neoplasms and in hepatocarcinomas (TCGA LIHC) at the somatic level." (PMID 33112832, 2020).
cancer (12 papers, 2008 to 2026). A tumor composed of atypical neoplastic, often pleomorphic cells that invade other tissues. "Among the TFAP2 family members, TFAP2A, TFAP2B, and TFAP2E interact with β-catenin to inhibit or promote oncogenesis in different types of cancers." (PMID 40837414, 2025). "Compared with adjacent tissues, the expression of TFAP2A, TFAPB, TFAP2D and TFAP2E in cancer tissue was significantly increased." (PMID 37859819, 2023). "Similar to other family members, the overexpression of TFAP2E in comparison to normal tissue was rather characteristic for cancers, including LUAD (p < 0.01) but, surprisingly, not LUSC (p > 0.05)." (PMID 36831334, 2023). "TFAP2E normally represses DKK4 promoter activity through direct binding, hence, low or no TFAP2E expression leads to DKK4 overexpression seen in CRC cell lines and cancer specimens." (PMID 25622259, 2015).
tumor (8 papers, 2011 to 2025). "The observed phenomenon whereby BRAF mutated tumours demonstrate resistance to 5-FU-based chemotherapy may be associated with the phenomenon of differential changes in TFAP2E promoter methylation." (PMID 26097884, 2015). "At present, the research on TFAP2D and TFAP2E in tumor is rare, compared to other genes in TFAP2 family." (PMID 37859819, 2023). "The controversy indicates that the influences of the complex cellular regulatory network and undiscovered interactions with the tumor microenvironment on TFAP2E are indispensable." (PMID 37291585, 2023). "They found that hypermethylation conferred a survival advantage in these patients, and that patients with hypermethylation in TFAP2E presented with earlier stage tumours, had less invasion, fewer positive lymph nodes and had better tumour differentiation." (PMID 26097884, 2015). "TFAP2E, or transcription factor AP-2 epsilon, is a gene that we have found to have a potential tumor-suppressor function (and correlation between methylation and expression)." (PMID 21760961, 2011). "No consensus has been reached that TFAP2E gene hypermethylation correlates with the loss of its protein expression at the tissue level across all stages of the tumor." (PMID 37291585, 2023). "Univariable analysis showed that age, molecular subtype, tumor TNM staging, TFAP2A, TFAP2B, TFAP2C and TFAP2E were important factors affecting the survival of BLCA patients." (PMID 37859819, 2023). "TFAP2E is a member of the AP2 family of transcription factors 6 and has a putative link as a tumour suppressor." (PMID 26097884, 2015).
gastrointestinal disease (1 paper, 2025). A disease that occurs in the gastrointestinal system, excluding the hepatobiliary system. "The prominence of TFAP2E among frequently correlated family members aligns with its documented pleiotropic functions in gastrointestinal diseases, in which the gut microbiota plays an established pathogenic role." (PMID 41373739, 2025).
TFAP2E also shares sentences with these, for which no sentence is quoted: chondrosarcoma (1 paper); diffuse large B-cell lymphoma (1); Hearing impairment (1); metastatic colorectal cancer (1); metastatic melanoma (1); microcephaly (1); osteoarthritis (1); prostate carcinoma (1); retinoblastoma (1); sarcoma (1); Waardenburg syndrome (1).